CTLA4 (cytotoxic T-lymphocyte associated protein 4)
Diseases named in the same sentence as CTLA4 in open-access papers (continued):
Sharing a sentence is not in itself a finding about the gene and the disease.
cancer (continued). "Therefore, blocking CTLA-4 reactivates T cells and restores their ability to attack cancer cells." (PMID 35911673, 2022). "The two most potent examples of T cell immune checkpoint molecules, anti-CTLA-4 and anti-programmed cell death protein 1 (PD-1) antibodies, provide a synergistic effect to regulate antitumoral immunity in a complementary manner that has revolutionized cancer treatment." (PMID 36679904, 2022). "Their study on the immunological checkpoints PD1 and CTLA-4 indicated that they played a “brake” role in immune activity and recommended that hindering immune checkpoints might reawaken T cells and more efficiently eradicate cancer cells." (PMID 36363529, 2022). "Given the unprecedented predictive value of PD-L1 and CTLA-4 expression in immunotherapy, investigating the different regulators of PD-L1 and CTLA-4 expression that may influence immunotherapeutic efficacy will contribute to the individualized clinical management of cancer patients." (PMID 35510040, 2022). "Liu and other researchers found that PD-1/CTLA4 levels were relevant to the progression of various cancers and infiltration level of immune cells, and their expression levels were notably relevant to the survival rate of patients diagnosed with different cancers." (PMID 39279987, 2022). "In recent years, lots of immunotherapy drugs, from monoclonal antibody against cytotoxic-T-lymphocyte-associated protein 4 (CTLA-4), programmed cell death protein 1 (PD-1) and PD-1 ligand 1 (PD-L1), to CAR T cell therapy, are approved by U.S. Food and Drug Administration (FDA) for cancer treatment." (PMID 35428347, 2022). "Therefore, we further investigated whether CTLA4-PD-L1 DNA or proteins act as the therapeutic and preventive cancer vaccines in a rat iCCA model." (PMID 36341387, 2022). "Recently, the combination of two inhibitory checkpoints (i.e., ipilimumab (anti-CTLA-4 and nivolumab (anti-PD-1) has also joined the list of approved drugs, showing good therapeutic efficacy in several studies and thus paving the way for new clinical trials in different types of cancers." (PMID 35301281, 2022). "Moreover, it has been reported that #0 Cancer therapy, #3 PD-L1 expression, and #11 CTLA-4 could be clustered into PCa immunotherapy by ICI." (PMID 36389756, 2022). "Notably, SLC2A1 is remarkably positively correlated with CD274 (PD-L1) and CTLA4 in most cancers." (PMID 36358765, 2022). "Thus, it might be hypothesized that IL2-GD2 ab strengthened the RT-induced immunogenic-inflammatory wave in cold TME, while anti-CTLA-4 was used to prevent the “anti-inflammatory” wave boosted by cancer cells." (PMID 35877226, 2022). "The anti-CTLA-4 monoclonal antibody ipilimumab, anti-PD-1 monoclonal antibodies cemiplimab, nivolumab, and pembrolizumab, and anti-PD-L1 monoclonal antibodies atezolizumab, avelumab, and durvalumab overcome immune checkpoints, allowing the immune system to target cancer cells." (PMID 35770005, 2022). "Given the acknowledgment that immune checkpoint blockade (ICB) cancer immunotherapy in accordance with the inhibition of key immune checkpoints, we assessed some representative molecules and discovered that PD-1, PD-L1, and CTLA4 were significantly increasingly expressed in the C1 group." (PMID 36482907, 2022). "Furthermore, high expression of CTLA-4 on TILs was significantly associated with a pCR and a better chemotherapy response (OR = 7.94, 95% CI: 0.9–70.12, p = 0.06) based on the MDACC Residual Cancer Burden Index in our cohort with TNBC." (PMID 33823818, 2021). "Interestingly, some studies show that the primary response to anti-CTLA4 antibodies required a high-level exposure of MHC-1 on the surface of cancer cells at baseline; on the other hand, the response to anti-PD-1 antibodies is linked to a pre-existing IFNγ transcriptome signature." (PMID 34638337, 2021).
cancer (continued). "In addition, we consider that Epimedium and ICT might sensitize the cancers to anti-PD-1/PD-L1 or anti-CTLA4 via increasing the infiltration of CD8+ T cells, since immune checkpoint blockade therapies often fail in the patients with poor T cell infiltration." (PMID 33460401, 2021). "Our findings showed that the AMPK activator, AICAR, exhibited synergistic antitumor effects when combined with anti-PD-1 and anti-CTLA4 antibodies, suggesting that AMPK activators could be considered to complement anti-PD-1 and anti-CTLA4 therapy to improve the outcomes of cancer patients." (PMID 34649584, 2021). "The blockade of PD-1 or CTLA-4 pathway could enhance the immune response of cancer patients." (PMID 35111663, 2021). "The concept that the CTLA-4 and PD-1 receptors might be utilised by cancer cells to avoid the immune system led to the development of monoclonal antibodies that could inhibit these receptors, with the hope that targeting them would lead to a more effective anti-tumour response from T lymphocytes." (PMID 34357131, 2021). "This has culminated with the approval of anti-Cytotoxic T-Lymphocyte-Associated protein 4 (CTLA-4) and Programmed Death (PD)-1/PD-Ligand 1 monoclonal antibodies (mAbs) and CD19-targeted Chimeric Antigen Receptor (CAR)-T-cell infusions as frontline therapies for a variety of cancers." (PMID 33572260, 2021). "In mice having Bacteroides (mainly B. fragilis) and Burkholderia in the guts, different cancers displayed slower growth, and the mice experienced reduced immunotherapy-induced intestinal epithelial cell necrosis, when they were treated with the anti-CTLA-4 antibodies." (PMID 34203292, 2021). "Importantly, this study showed that anti-CTLA-4 and anti-PD-1 antibodies could reverse the antagonistic impact exerted by cancer cells on the TME." (PMID 34268109, 2021). "Immune checkpoint molecules, such as CTLA-4 and PD-1, play critical roles in regulating immune responses and suppressing immune effector cells, thus leading to the development of ICIs, which have proven to be exceptionally effective in some cancers in some patients." (PMID 34578321, 2021). "In addition, as the immune checkpoints are often used to escape immune surveillance by cancer cells, we also explore the response of checkpoint inhibitors (e.g., PD-1, PD-L1, PD-L2, CTLA-4, LAG3, and TIM-3) and discovered that many of these genes significantly increased in the high-risk group." (PMID 34712325, 2021). "In multiple pathogen infections and cancers, activated NK cells have been shown to express the immune checkpoints programmed cell death protein 1 (PD1), cytotoxic T lymphocyte-associated antigen 4 (CTLA4), and T cell immunoreceptor with Ig and ITIM domains (TIGIT)." (PMID 33670082, 2021). "Upon activation, conventional T cells in cancer patients could up-regulated CTLA4." (PMID 33507988, 2021). "Therefore, it is suggested that using IDO inhibitors combined with ICIs could improve the anti-cancer function of anti-CTLA-4 antibodies." (PMID 34572263, 2021). "Immune checkpoints, including programmed death-1 (PD-1), cytotoxic T-lymphocyte-associated protein 4 (CTLA-4) and T cell immunoglobulin mucin domain-containing-3 (TIM3), have been found to be pivotal switches in immunity adjustment for T lymphocytes and are used in routine cancer therapy at present." (PMID 34680598, 2021). "Thus, CTLA-4 may involve in cancer development and progression and exerted an important function in cancer immunosurveillance." (PMID 33819967, 2021). "Despite great hopes, checkpoint inhibitors targeting either PD-1, PD-L1 or cytotoxic T-lymphocyte-associated protein 4 (CTLA-4) applied as monotherapies have not yielded clinical improvements for PDAC patients in contrast to therapeutic successes in other cancers." (PMID 34439389, 2021).
cancer (continued). "For instance, the approved immune checkpoint blockade drugs which target cytotoxic T-lymphocyte antigen 4 (CTLA-4) and programmed cell death 1 (PD-1) or its ligand, programmed cell death ligand 1 (PD-L1), have shown efficacy in prolonging the overall survival of patients with various cancers." (PMID 33628850, 2021). "The combination of CTLA-4 and PD-1 inhibitors could be a good approach for cancer therapy." (PMID 34193050, 2021). "Although the most advanced knowledge has been generated around the therapies targeting PD-1/PDL-1 or CTLA-4, there are multiple other important pathways that may impact the immune response to cancer involving many genes, in particular LAG-3, TLR-4, VISTA, TIM-3, TIGIT, ICOS, OX40, and GITR5." (PMID 33911192, 2021). "Antibody-based drugs targeting cytotoxic T-lymphocyte-associated protein 4 (CTLA-4), programmed cell death protein 1 (PD-1) and programmed cell death protein-ligand 1 (PD-L1) have proven superior to existing chemotherapy and radiation approaches for multiple cancer types." (PMID 34440039, 2021). "CTLA-4 blockade could enhance antitumor immunity when combined with cancer vaccines." (PMID 33106940, 2021). "Therefore, it is not surprising that molecules that block adenosine binding to the A2a receptor and molecules that inhibit the activity of the CD39 and CD73 enzymes have been developed and used in combination with anti-PD-1 or anti-CTLA-4 antibodies in early phase clinical trials in cancer patients." (PMID 34200219, 2021). "Taken together, this developed camelid-specific anti-CTLA-4 Nanobody 3hCTL55, selected from a high-quality immune library by phage display technique, may be effective for further study about cancer diagnosis and cancer-therapy purposes." (PMID 35083014, 2021). "Therefore, depletion of Treg cells is being studied as a possible cancer therapy that could improve the therapeutic effect of PD-1/PD-L1 and CTLA-4 inhibitors." (PMID 33946818, 2021). "Therefore, CTLA4 became one of the targets in cancer therapy." (PMID 33802937, 2021). "In addition, interpretation may be complicated by the inclusion of two cancer types and two PD-1 inhibitors, plus the fact that a number of patients additionally received a CTLA-4 inhibitor, radiation and/or steroids." (PMID 34321489, 2021). "Considering previous results on the association between gut microbiota composition and clinical response and the effect of SCFA on the immune system, even at distant site, we hypothesized that anti-cancer response due to anti-CTLA-4 blockade may be influenced by systemic microbial SCFA." (PMID 32358520, 2020). "Therefore, it is likely multiple cancer types may well respond to anti-CTLA-4 therapy if appropriate antibodies are employed." (PMID 31991588, 2020). "Moreover, in metastatic melanoma, through immune exclusion, caused by deficient recruitment of dendritic cells (DC CD1031), the activation of the Wnt signaling pathway leads to the immunotherapy resistance of cancer cells against anti-PD-L1 and anti-CTLA-4 ΜοAbs." (PMID 32344837, 2020). "The identification of the candidate key genes and enriched signaling pathways provides potential biomarkers for autoimmune thyroid dysfunction related to anti-CTLA-4 therapy and might contribute to the future diagnosis and management of IRAEs for cancer patients." (PMID 32500465, 2020). "TERT mutations may be a potential biomarker for anti‐CTLA4 treatment, but not programmed cell death‐1 (PD‐1)/programmed cell death‐L1 (PD‐L1) blockade and combination treatment across pan‐cancer types." (PMID 32810393, 2020). "The recognition of the role of immune checkpoints, particularly cytotoxic T-lymphocyte antigen (CTLA)-4 and programmed cell death (PD)-1, has shed new light on the mechanisms of negative regulation of the immune system and opened a new era in the clinical application of immunotherapy in cancer." (PMID 32727102, 2020).
cancer (continued). "Therefore, combination blocking HLA-G with other immune checkpoints (PD-1/PD-L1 or CTLA-4) represents an inspiring strategy for cancer treatment, which may help overcome the resistance routinely developing in patients treated with a single immunotherapy." (PMID 33425752, 2020). "However, it remains to be determined whether the combination of PD-1 and CTLA4 inhibitors has greater efficacy than monotherapy in these cancers." (PMID 33072070, 2020). "As a result of the high CTLA-4 expression on Tregs and its significant role in the suppressive mechanisms of Tregs, it appears that the therapeutic targeting of this receptor could improve cancer therapy." (PMID 33519807, 2020). "One of the most exciting areas in cancer immunotherapy has been immune checkpoint blockade, with the 2018 Nobel Prize in Medicine awarded to James Allison and Tasuku Honjo for their roles in the discovery of two targets for immune checkpoint therapy, CTLA-4 and PD-1." (PMID 33008010, 2020). "Therefore, the FDA approved ICIs that block the interaction between CTLA-4 and its ligand or block the interaction between PD-1 and PD-L1, thereby restoring cytotoxic T cell immune response in recognizing and destroying cancer cells thus preventing growth of tumors." (PMID 33585182, 2020). "This review—by addressing the primary details of CTLA-4 and PD-1 pathways and the results from clinical studies that evaluated the combination of ipilimumab and nivolumab—aims to support future research in combination therapy as the new standard of care for cancer treatment." (PMID 32580338, 2020). "Hence, in the context of cancer, CTLA-4c.-658*C allele (higher expression of CTLA-4 molecule) may confer increased risk of cancer development." (PMID 33519815, 2020). "Interestingly, systemic short chain fatty acids from gut microbial metabolites could limit antitumor effect of CTLA-4 blockade in hosts with cancer." (PMID 32680511, 2020). "Hence, the high expression of PDL1 in BD3 tumors would be associated with the immune evasion mechanisms deployed by cancer cells at the invasive front in these tumors, while the overexpression of PD1 and CTLA4 genes in BD1 tumors would reflect their comparative higher immunogenicity." (PMID 32719800, 2020). "However, CTLA-4 may exist on human NK cells and may modulate their effector functions in cancer immunity." (PMID 31156651, 2019). "Immune-checkpoint targeted therapy using cytotoxic T lymphocyte-associated protein 4 (CTLA4), programmed cell death protein 1(PD-1) and programmed cell death ligand-1(PD-L1) inhibitors to overcome immune tolerance TOWARD cancer cells has been one of the major breakthrough in cancer therapy." (PMID 30778352, 2019). "Hence, the expression level of CTLA-4 in cancer cells or microenvironments may constitute a potential predictive or prognostic biomarker of malignant disease patients." (PMID 31485274, 2019). "The results from the studies could provide additional insights into immunosuppressive mechanisms in TME and the significance of CTLA-4 plus PD-1 blockade in respective types of cancer, and help in identifying the combination dose with desired efficacy and adverse event profile." (PMID 31196207, 2019). "While checkpoint inhibitors targeting PD-1 or CTLA-4 represent the most effective tools to successfully treat a fraction of otherwise incurable cancer patients, their combined use with therapeutic antibodies blocking NKG2A and KIR may further extend the benefit to a large proportion of patients." (PMID 31231370, 2019). "Indeed, the major finding that targeting the CTLA-4 pathway via antibody blockade can enhance anti-tumor responses was first demonstrated in a preclinical mouse model, highlighting the relevance and usefulness of murine cancer model systems." (PMID 31998326, 2019).
cancer (continued). "The crucial role of CTLA-4 and PD-1 in regulation of a tolerogenic immune response opens up for a blockage of both checkpoint molecules that may have great therapeutic potential in terms of activating an immune response against the cancer cells." (PMID 31134056, 2019). "Extensive preclinical murine cancer models and clinical development efforts have been undertaken for a number of co-inhibitory, or immune checkpoint, receptors that have been characterized as identifying exhausted T cells, including CTLA-4, PD-1, LAG-3, TIM-3, and TIGIT." (PMID 30858925, 2019). "In addition, combined treatment sensitizes cancer cells to anti-CTLA4 therapy." (PMID 31817534, 2019). "Interestingly, anti-CTLA-4 antibody showed a unique curative effect in anti-PD-1-resistant cancer." (PMID 31156651, 2019). "Cancer immunotherapy is employed by blocking the multiple negative regulatory proteins of T-cell activation known as cytotoxic T-lymphocyte-associated antigen 4 (CTLA4), programmed death-ligand 1 (PD-L1), and programmed death 1 (PD1)." (PMID 30978984, 2019). "In addition, anti-CTLA-4 antibody therapy may be effective against regulatory T cells in the cancer immunosuppressive microenvironment." (PMID 31671581, 2019). "Notably, the blockade of immunosuppressive checkpoints, such as T-lymphocyte-associated antigen 4 (CTLA4), programmed cell death 1 (PD1) protein, and programmed cell death-ligand 1 (PD-L1), has demonstrated objective clinical responses in various cancers and other malignant neoplasms." (PMID 30871634, 2019). "Therefore, multi-targeting of LAG-3, TIM-3, PD-1, and/or CTLA-4 may serve as a next generation cancer immunotherapy." (PMID 31292525, 2019). "Together with James P. Allison, who worked on another co-inhibitory receptor called cytotoxic T-lymphocyte-associated Protein 4 (CTLA-4), Tasuku Honjo was awarded the Nobel Prize in Physiology or Medicine 2018 for the discovery of cancer therapy by inhibition of negative immune regulation." (PMID 31263684, 2019). "James P. Allison proposed that the CTLA-4 blockade could encourage T cells to fight cancer cells." (PMID 31683894, 2019). "Biomarkers such as cytotoxic T-lymphocyte-associated antigen 4 (CTLA-4) ligands, interleukin-10, transforming growth factor β (TGF-β), and programmed death-ligand 1 (PD-L1) are well-known molecules involved in escape from host immune surveillance and are associated with cancer cell proliferation." (PMID 31366979, 2019). "Thus, blocking either CTLA-4 or PD-1 has emerged as a promising anti-cancer strategy." (PMID 30319626, 2018). "Indeed, analyses of CTLA-4 and sCTLA-4 in cancer cells lines suggest that some tumors may use either or both isoforms as part of a previously overlooked immune evasion strategy." (PMID 30319637, 2018). "Cancer immunotherapies have been hailed as the fourth pillar of cancer treatment and its great success in the clinic has led to the Nobel prize recently being awarded to James Allison and Tasuku Honjo for recognition of their discovery of the checkpoint molecules CTLA-4 and PD-1 respectively." (PMID 30513816, 2018). "ICBs targeting the cytotoxic T-lymphocyte-associated protein 4 (CTLA-4), the programmed cell death protein 1 (PD-1) and its ligand (PD-L1) have shown unprecedented durable responses and are now part of the standard of care for patients with different cancer types." (PMID 30345255, 2018). "Lastly, since the new frontier of cancer immunotherapy is the employment of immune checkpoint inhibitors (i.e., against PD-1, PD-L1, CTLA-4) further studies are needed to clarify whether IL-33 conditioning may increase the therapeutic response to checkpoint blockade in cancer patients." (PMID 30483263, 2018). "Also, it is notable that a new phase I/II clinical trial (NCT03459222) has recently been opened to investigate the efficacy of triple targeting LAG-3, PD-1, and CTLA-4, which may be a novel combinatorial strategy in cancer treatment and autoimmune disorders." (PMID 30603054, 2018).